IL2 (interleukin 2)
Diseases named in the same sentence as IL2 in open-access papers (continued):
Sharing a sentence is not in itself a finding about the gene and the disease.
tumor (continued). "In tumours, however, binding of PD-L1 to its PD-1 receptor on activated T cells results in T-cell suppression and immune escape by inhibiting perforin/granzyme production, suppressing IL-2 and IFN-γ production and promoting apoptosis, effectively inducing tumour growth." (PMID 37397243, 2023). "GSVA revealed that cell cycle-related pathways (e.g., MYC target and G2/M checkpoint), immune response pathways (e.g., IL-2 STAT5 signaling and TNF signaling via NF-κB), and aberrantly activated pathways (e.g., mTORC1 and PI3K/AKT/mTOR signaling) were dominant in tumor cells of APHC." (PMID 37336873, 2023). "Using this coculture model, we found that incubation with CMTM6-knockout tumor cells significantly reduced the expression of T cell activation markers (CD137 and CD69) and T cell effector cytokines (IL-2 and TNFα) compared to wild-type and CMTM6-reconstituted tumor cells." (PMID 37683639, 2023). "We also tested the levels of proinflammatory cytokines by ELISA and ELISPOT IFN-γ production after incubation with FAP− HepG2 tumor cells, and no significant changes in IL-2 or IFN-γ secretion or the IFN-γ response were observed." (PMID 38031188, 2023). "The hyposecretion of IL-2 and IFN-γ in peripheral blood is often detected in patients with advanced tumors, and the secretion of IL-10 increases, indicating that Th0 to Th2 differentiation is dominant during tumor growth." (PMID 36694223, 2023). "The findings indicated no tumor shrinkage, as five individuals in the first cohort showed attention-requiring toxicities (grade 3/4; attributable to high-dose IL-2) whereas those in the second cohort exhibited milder signs of toxicities (grade 1/2)." (PMID 38146364, 2023). "Treatment with IL-2 and LDH inhibitor invoked a shift from glycolysis towards oxidative phosphorylation, and IL-2 or IL-21 treatment in combination with LDH inhibitor increased stem cell memory T cell formation and reduced tumor growth." (PMID 37842241, 2023). "Employing this method, the liposomes have exhibited anti-tumor efficacy comparable to the free forms of IL-2 and anti-CD137 across various tumor models, but without any systemic toxicity." (PMID 37808190, 2023). "Notably, tumor immune‐related cytokines, including tumor necrosis factor (TNF)‐α, IL‐1β, IL‐2, IL‐6, IL‐17, CD4+/CD8+, IFN‐α, and IFN‐γ, were determined." (PMID 36951443, 2023). "When the tumor releases a large number of highly expressed costimulatory molecules of EVs, APCs or DCs can directly present the antigen to CD8+ T cells, stimulate their synthesis of IL-2 and proliferation and differentiation into CTL with a specific killing effect on tumor cells." (PMID 36872320, 2023). "Thus, while IL2-MSA can promote Treg expansion, the combination of IL12-MSA and IL2-MSA appears to favor SIY-reactive CD8+ T cells in the TdLN and tumor." (PMID 37669107, 2023). "The therapeutic activity of IL2-7NP2-TNFmut was compared with IL2-F8-TNFmut in immunocompromised tumor-bearing mice, in which FAP was expressed on tumor cells whereas EDA was present in the tumor stroma." (PMID 37092450, 2023). "We previously found that combined administration of IL12-MSA and IL2-MSA could drive the effector differentiation of dysfunctional, tumor-reactive CD8+ T cells and extend the survival of mice with KP lung tumors." (PMID 37669107, 2023). "Quite a different tumor marker was selected during Selectikine (NHS-IL-2Lt, EMD521873) development, which consists of an IL-2 low-toxicity mutant (D20T) fused at the N terminus to a humanized NHS antibody targeted against DNA and histone complexes released at the necrotic core of tumors." (PMID 36839658, 2023). "TILT-123 is an ADV with two potent anti-tumor cytokines (TNF-α and IL-2)." (PMID 36604694, 2023). "This confirms the similar observations of giving CY before immunotherapy to achieve better antitumor or immunostimulating efficacy, whereas CY given at the time of immunotherapy with systemic IL-2 led to enhanced tumor growth rather than tumor inhibition." (PMID 37746303, 2023).
tumor (continued). "Furthermore, IL33 expression levels were positively correlated with those of Th1 cytokines (IL2 and IFNG) and Th2 cytokines (IL4 and IL10) in 41 tumor tissues." (PMID 37056569, 2023). "Decreased tumor weight.Increased secretion of TNF-α, IFN-γ, and IL-2.Decreased secretion of IL-4." (PMID 38136228, 2023). "Th1 cells are characterized by the production of IL-2 and IFNγ, which suppresses tumor progression at least by supporting CD8+ T cell function, facilitating recruitment of antigen-presenting cells, and inhibiting tumor angiogenesis." (PMID 37620312, 2023). "Furthermore, both IL-2 and IFN-γ levels were increased in treated tumour tissues compared with those in untreated patients." (PMID 37299554, 2023). "At the same time, the upregulation of PD-L1 on dendritic cells inhibits the secretion of IL-2, IL-10, INF-γ, INF-α and other cytokines by T lymphocytes in the tumor microenvironment, downregulates the immune “surveillance” function of T cells, and mediates tumor immune escape." (PMID 37006252, 2023). "We also obtained similar changes in the protein expression of TNF-α, IFN-γ, and IL-2 in the right non-irradiated tumor via Western blot as seen in the PCR analysis." (PMID 36835310, 2023). "In line with the cell populations, cytokine analysis revealed that combinational treatment also increased the population of tumor-infiltrating T cells producing IL-2 and IFN-γ (but not TNF-α) significantly more than anti-PD-1 blockade alone." (PMID 37651197, 2023). "In this circuit, IL-2 expression is driven by tumor-specific synNotch receptors independent of CAR/TCR activation." (PMID 37308558, 2023). "As a result of these measurements in the CT-26 tumor model that was formed in mice, a non-significant statistical difference in tumor sizes was observed in the 5FU/IL2/CD2 nanoplex groups when compared with the control group (p > 0.05)." (PMID 36839637, 2023). "IL-2-activated neutrophils, macrophages, and NK (natural killer) cells have a role in non-specific immunity against tumor." (PMID 37520880, 2023). "IL-2 and IFN-γ cytokines are important regulators for the anti-tumor activity of CAR T cells." (PMID 36835603, 2023). "IL-2 promotes TIL proliferation, activation, and tumor-killing activity." (PMID 36810079, 2023). "It is therefore possible inducing local production of IL2 by T cells in the tumor microenvironment will have a therapeutically important impact on NK cell mediated ADCC even though exogenously administered IL2 did not." (PMID 34110453, 2022). "Similarly, the secretion of IL-2, IL-13, and TNF-α is significantly higher in tumour-conditioned media (TCM) derived from 1,4-dihydroxy quininib treated primary UM tumours vs. vehicle." (PMID 36698840, 2022). "KOMAP, a polysaccharide from P. eryngii, significantly increased the immune organ index, LPS- or ConA-induced splenocyte proliferation, serum levels of cytokines including IL-2, TNF-α and IFN-γ, as well as the activity of NK and CTL cells in tumor-bearing mice." (PMID 35585984, 2022). "LSFM and cyclic IF proved to be advantageous for the analysis of CAR T cell-tumor cell interactions, assessment of CAR T intratumoral distribution at cellular resolution and analysis of IL-2 influence on CAR T cells, which altered CAR T cell proliferation, location, and phenotype within the tumor." (PMID 35836798, 2022). "In a bilateral tumor setting, combination of TransCon TLR7/8 Agonist with systemic IL-2 potentiated tumor growth inhibition in both injected and non-injected tumors and conferred protection against tumor rechallenge following complete regressions." (PMID 36123697, 2022). "We found this therapy to be safe and allowed persistent transgene expression in the tumor over 3 weeks, regardless of anti-vaccinia IgG levels, however the amount of interleukin-2 produced in the tumors was insufficient to justify further clinical trials." (PMID 35431929, 2022).
tumor (continued). "However, by competitive IL2-consumption, immunosuppressive cytokine secretion (IL-10, TGF-β) or suppression of APCs via CTLA-4 they can also reduce anti-tumor immunity." (PMID 35159220, 2022). "Additionally, subsequent tumor analysis of soluble cytokine expression revealed that treatment with IMT plus PTX resulted in IFN-γ, IL-2, and IL-12 expression and Th2 response." (PMID 35214172, 2022). "Moreover, Ruxo increased TNF, IFN-γ, perforin, and IL-2 production by CD4+ TILs, essential effector molecules in anti-tumor immunity; similar increases of IFN-γ, perforin, and GzmB were also noticed in CD8+ TILs." (PMID 36008408, 2022). "However, thanks to genetic engineering techniques, IL-2 preferentially binds to CD8 and NK cell IL-2 receptors, refocusing IL-2 into the tumor microenvironment and ameliorating the off-target effects." (PMID 35296094, 2022). "CD8+ T lymphocytes identify and kill tumor cells playing a role in the anticancer immune response, and are usually supported by CD4+ T helper cells that release interferon-gamma (IFNγ) and interleukin-2 (IL-2)." (PMID 35958590, 2022). "In the future, our bispecific antibody may combine with cytokines enhancing NK proliferation and function such as interleukin-2 and interleukin-15 to potentiate NK-mediated ADCC against antibody-coated tumor cells and T regular cells." (PMID 36289396, 2022). "Upon anti-PSCA IgG4-TM mediated cross-linkage with PC3-PSCA tumor cells, UniCAR T cells were engaged for significant secretion of the pro-inflammatory cytokines TNF and IFN-γ, as well as the growth-promoting cytokine IL-2." (PMID 35454902, 2022). "Tumor-infiltrating Tregs showed increased TNF-α and IL-2 production after NEO." (PMID 36509285, 2022). "Second, in order to bypass TCR/CAR suppression by the tumor microenvironment, induction of IL-2 production must be independent of the TCR activation pathway (e.g. NFAT promoter induced IL-2 still requires TCR/CAR activation to be triggered)." (PMID 36520915, 2022). "Besides, eTregs can hamper the activation and tumor-killing capacity of CD8+ T cells and natural killer (NK) cells via depriving IL-2 owing to its high-affinity receptor CD25 on the cell surface." (PMID 35497874, 2022). "This study revealed that, after adjusting for tumor metastatic lymphoid node numbers, the patients who received auto-TIL–based ACT treatment had a longer relapse-free survival (RFS) and OS compared with the patients who received the IL-2 injection only." (PMID 35727633, 2022). "Distinct from our studies in immunodeficient mice, these paracrine IL-2 circuit cells failed to improve tumor control in an immune competent context." (PMID 36520915, 2022). "Here, visual examination of the BLT scans did not result in the detection of any differences in the CAR T cell biodistribution in the presence or absence of subcutaneous IL-2 injection under the tumor." (PMID 35836798, 2022). "To test whether nanobodies specific to the EIIIB domain of FN can be used for targeted delivery and persistence of cytokines in the tumor ECM, we expressed murine IL-2 fused to the NJB2 nanobody, previously shown to bind EIIIB with 2 nM affinity." (PMID 36712341, 2022). "With the rapid development of tumor immunotherapy, it has been found that CRS can be induced by a variety of immunotherapy methods, such as CAR T cell therapy, systemic IL-2 administration, PD-1 inhibitors and radiation therapy." (PMID 35748951, 2022). "When high levels of IL-2 are available, cells that express CD25, i.e. natural killer cells and T lymphocytes, will be activated, leading to an important immune response towards the tumor." (PMID 35361879, 2022). "For example, a half-life-extended super mutant IL-2 conjugated to a tumor-targeting antibody allowed more efficient CTL stimulation and expansion in the TME, resulting in significantly improved complete response rate and lower tumor relapse in vivo." (PMID 35432319, 2022).
tumor (continued). "The chosen anti-PD-1 scFv could restore IL-2 and IFN- production by Jurkat T cells co-cultured with PD-L1 positive tumor cells." (PMID 36341340, 2022). "Additionally, other cytokines such as interleukin-2 (IL-2), IL-24, IFN, tumour necrosis factor (TNF) α, and soluble CD80 and CCL3 have been used in the study of viral treatment of tumours." (PMID 36552019, 2022). "Of note, the mHsp70 positivity on tumor cells was reduced 1.44 ± 0.1 fold after a 36 hour co-incubation with anti-Hsp70 CAR T cells and 1.5 ± 0.3 fold after a 24 hour co-incubation with TKD/IL-2 activated NK cells." (PMID 35720311, 2022). "This trike could bind to the HN of the NDV infected tumor cells from one side and to the CD28 receptor on the T cells from the other side, while IL-2 promoted T cells function." (PMID 36311790, 2022). "Likewise, effector CD8+ T cells can inhibit tumor development and secrete several cytokines, including IFN-γ and IL-2." (PMID 35535221, 2022). "Therefore, the trimer high affinity complex on Treg cells consumes a large amount of IL-2, which requires a higher dose of IL-2 to achieve cytotoxic T lymphocyte (CTL)–mediated anti-tumor immunity." (PMID 36569954, 2022). "Several factors could affect apparent number of CD4+ T cells in tumor: recruitment (CXCL9/10), proliferation (IL‐15), and death (IL‐2)." (PMID 34898004, 2022). "The in vivo administration of pamidronate/Zol and low-dose IL-2 also triggered the proliferation of γδT cells in clinical trials and engaged the anti-tumor response without appreciable toxicity in patients." (PMID 35747139, 2022). "The rate-limiting enzyme involved in tryptophan catabolism, indoleamine 2,3-dioxygenase (IDO), is released by tumor cells and can inhibit the upregulation of NKp46 and NKG2D via blockade of IL-2, again limiting the NK cell’s ability to recognize and kill tumor cells." (PMID 35203256, 2022). "And even without ZOL or IL-2 supplementation, he experienced depleted tumor activity, tumor size reduction, and improved quality of life during and after the treatment." (PMID 35740670, 2022). "Six of eight transduced patient samples produced IL-2 upon autologous tumor stimulation and survived longer than non-transduced TILs." (PMID 36389779, 2022). "However, consistent with the TDM-1 experiments, tumours treated with U3-1402 exhibited higher levels of pro-inflammatory cytokines such as IFN-γ, TNF-α, and IL-2, and in vivo depletion of CD8+ cells reduced its anti-tumour efficacy." (PMID 36046842, 2022). "This is the case of immunocytokine and antibody-drug conjugates (ADC) where pro-inflammatory payloads (e.g., IL2, IL12) and chemical cytotoxic agents can be delivered to the tumor niche, leading to low systemic adverse effects and potentiating their anti-cancer activity." (PMID 35267633, 2022). "Thus, the ablation of genetic NR2F6 strongly enhances the secretion of interleukin-2 (IL-2), interferon-γ (IFN-γ), and tumor necrosis factor-α (TNF-α) both at tumor sites and ex vivo, thereby promoting antitumor immunological responses." (PMID 35907841, 2022). "The treatment with radiotherapy or anti-PD-L1 antibody in the miR-21 knock-in mice diminished tumor weight and volume, along with decreased CD3+CD8+ positive cells, serum IL-2 and IFN-γ levels, and lower PD-L1 expression, but augmented apoptosis of T and BC cells." (PMID 35295718, 2022). "Experiments showed that TT-LDCP nanoparticles that co-delivered PD-L1 siRNA and IL-2 Pdna could reverse the immunosuppressive TME of HCC by increasing tumoral infiltration CD8+ T cells and promote the maturation of tumor-infiltrating DCs." (PMID 36014696, 2022). "Anchoring of anti-CD137 and IL-2 to PEGylated liposomes allowed for an effective anti-tumor response, without adverse systemic effects, in multiple tumor models." (PMID 35203256, 2022). "Indeed, IL-2 has been FDA approved for use in cancer immunotherapy since the 1990s, to stimulate anti-tumor Teff cells and natural killer (NK) cells." (PMID 36591309, 2022).
tumor (continued). "We review some beneficial bacteria that act on DCs, NK cells, cytotoxic T cells, and helper T cells to promote the secretion of the pro-tumor cytokines IFN-1, IFN-γ, and IL-2 and down-regulate the secretion of TNF-α, IL-6, IL-10, and IL-22, thus exerting anti-tumor immune effects." (PMID 36438840, 2022). "Meanwhile, the ratios of CD8+IFN-γ+ T, CD8+ IL-2+ T, CD8+TNF-α+ T, and CD8+Granzyme B+ T cells in the splenocytes of Cal/ICG@MPs with 808 nm laser irradiation-treated mice was significantly increased after tumor antigen restimulation." (PMID 35589680, 2022). "Regarding the establishment of tumor-promoting inflammation, KRAS was shown to be capable of inducing cytokine secretion such as IL-6 and reduced secretion of IFNγ, TNF, and IL-2 by different stromal cell types, e.g., fibroblasts, myoblasts and epithelial cells." (PMID 35965494, 2022). "As an alternative to single-cell preparation and sorting, TILs can also be expanded directly from tumor materials by culturing the material for several weeks in the presence of stimulatory agents (IL-2, with or without anti-CD3 stimulus)." (PMID 35464481, 2022). "The results revealed that the INTERFERON_GAMMA_RESPONSE pathway, the IL2_STAT5_SIGNALING pathway, the TNFA SIGNALING VIA NKFB pathway, the UV_RESPONSE_UP, IL6_JAK_STAT3_SIGNALING pathway, and the HYPOXIA pathway were upregulated in tumor-infiltrating cells." (PMID 35812372, 2022). "Regardless of IL-2 treatment, tumors began to grow in all mice in the two groups 1 month after tumor inoculation." (PMID 36497152, 2022). "Since the release of IFN‐γ and IL2 from Th1 cells can promote differentiation of naïve CD8+ T cells into cytotoxic T cells, Th1 cells are considered the most prominent subtype for anti‐tumour immunity." (PMID 35758207, 2022). "Furthermore, RNA was isolated from the splenocytes, and the expression of IL-2 and IFN-γ was assessed; their levels were significantly increased in the tumour-implanted Ack1 KO mice." (PMID 36376335, 2022). "Second, the release of some cytokines, such as IL-2 and IL-15, as well as subsequently stimulated IFN-γ, can stimulate the enhancement of avelumab-triggered cytokine production and degranulation in NK cells while increasing lytic activity against tumor cells." (PMID 35634343, 2022). "Moreover, tumour immunity, such as the inflammatory response, IL6/JAK/STAT3 signalling and IL2/STAT5 signalling, was prominently enriched in parental HCC cells." (PMID 36275751, 2022). "In mice treated with Imprime, a significantly higher percentage of CD8 T cells expressed both Ki67 and GrzB, and when isolated and stimulated with anti-CD3/CD28 monoclonal Abs, exhibited enhanced proliferation and production of critical anti-tumor effector cytokines IFN-γ, IL-2, and TNF-α." (PMID 35692755, 2022). "According to the results of the Western blot, CTP significantly increased the levels of CD4, CD8, and IL-2, and reduced the levels of CTLA4 and PD-L1 in the tumor, and CTLA4 and PD-1 in the spleen of ApcMin/+ mice; this underscored the pivotal role of IL-2 in the immune response." (PMID 35662701, 2022). "Mechanistically, OVV-CD19BiTE is capable of recruiting T cells to a tumor and stimulating its proliferation, even in the absence of exogenous IL-2, compared with its parental OVV." (PMID 35228544, 2022). "Tumor suppression occurred in the absence of IL-2 treatment, although co-expressing IL-2 with shFDPS on the same vector appears to have increased potency." (PMID 36275712, 2022). "In an immune-tolerant state that endogenous IL-2 is thought to be not sufficient for effector T cells to be fully activated, exogenous IL-2 can trigger Teff to exert an anti-tumor effect." (PMID 35983059, 2022). "Our results suggest that changes in IL-2, IFN-gamma, and THBS-4 expression may sensitize the tumor to long term sustained treatment response by triggering a state of enhanced immune activation." (PMID 35205763, 2022).